RN7SL558P (RNA, 7SL, cytoplasmic 558, pseudogene)
Gene: Miscellaneous RNA gene on chromosome 4 (39,761,000 to 39,761,298, forward strand). Ensembl gene ENSG00000243260.
Homologues: Orthologues: chimpanzee Metazoa_SRP (99% identical), macaque Metazoa_SRP (96% identical). Paralogues in human: RN7SL1 (81% identical), RN7SL2 (80% identical), RN7SL3 (80% identical), RN7SL743P (80% identical), RN7SL851P (80% identical), RN7SL296P (79% identical), RN7SL49P (79% identical), RN7SL679P (79% identical), RN7SL15P (78% identical), RN7SL88P (78% identical), RN7SL147P (78% identical), RN7SL329P (78% identical), and 704 more.